IL6 (interleukin 6)
Diseases named in the same sentence as IL6 in open-access papers (continued):
Sharing a sentence is not in itself a finding about the gene and the disease.
cancer (continued). "More recently, it was also shown that IL-6 trans-signaling works as a novel potent inducer of autophagy in myotubes inducing pathway that may be important in cancer cachexia development." (PMID 31114509, 2019). "Mechanically, previous reports indicated that IL-6 could regulated a bunch of key genes to promote cancer cell EMT and stemness, such as Fra-1 and NRF2." (PMID 30989585, 2019). "Therefore, targeting IL-6/Sta3 signaling axis potentially improve the efficacy of cancer immunotherapy." (PMID 30885232, 2019). "Moreover, chip-PCR analysis showed that STAT3 bind directly the FOSL1 gene promoter in cancer cell lines stimulated with IL6." (PMID 31438567, 2019). "However, Il-6 levels were significantly reduced by adding JEKHT to the treatment regimen in malignant tumors (P = 0.03) that also expressed significantly higher levels of Il-6 than benign tumors (P = 0.04)." (PMID 30640711, 2019). "These, in turn, enhance cancer cell survival through an increase of cyclin D1 and cyclin E, which stimulate cellular proliferation, and the increase of several cytokines, e.g. IL-1, IL-2, and IL-6, with pro-inflammatory action." (PMID 31766196, 2019). "IL-6 is a four-helical cytokine with pleiotropic activities, which is synthesized by many cell types upon appropriate stimulation and which can act on many cell types during several disease states such as inflammation and cancer." (PMID 31694340, 2019). "Additionally, the absence of B7-H3 led to decreased secretion of cytokines, such as interleukin (IL)-6 and vascular endothelial growth factor (VEGF), as well as a decline in migration and invasion ability in cancer-associated fibroblasts (CAFs)." (PMID 31998637, 2019). "Furthermore, this elevation in the IL-6 level that was detectable in plasma indicates the role of IL-6 in cancer biology, as well as the clinical implication of IL-6 as a biomarker to detect fatigue or follow the responses to therapy." (PMID 31010015, 2019). "In addition, the activation of the PI3K-pAkt-mTOR pathway triggered by IL-6 was shown to be related to cell proliferation and metastasis in a variety of cancers." (PMID 31252615, 2019). "To further identify whether cytokines secreted by CAFs influence cancer cell growth and chemotactic attraction detected above, we examined the downstream proteins of IL-6 and RANKL in co-cultures with TM40D cells." (PMID 31595162, 2019). "Several inflammatory mediators, such as TNF-α, IL-6, and IL-10, might have an effect in the initiation and progression of cancer, so the inflammatory microenvironment can be relate to the tumorigenesis of liver." (PMID 31340754, 2019). "Due to the flagellin-induced IL6, which is known to inhibit apoptosis in many cancer cell types, we measured the effects of flagellin on the caspase-1 activity of the C26 cells together with either TLR5 antagonist or genipin, which inhibits NLRP3-mediated inflammasome activation." (PMID 31731747, 2019). "The cross-talk between adipocytes and cancer cells is mediated by cytokines (specifically IL-1, IL-6 and TNF-α), adipokines, including APN and other molecules, released by adipose tissue, able to control proliferation and invasion of different cancer cell types." (PMID 30781341, 2019). "MCT-1 and IL-6/IL-6R pathway can together advance cancer stemness effects." (PMID 30885232, 2019). "Cancer metastasis signaling was linked with JAK kinase, Wnt family member 9A (WNT9A), IL6, and prostaglandin-endoperoxide synthase 2 (PTGS2); whereas interleukin 1 receptor associated kinase 4 (IRAK4), and histone h3 were associated with p38MAKP signaling pathway." (PMID 30972102, 2019). "IL-6 has also been shown to upregulate DNA methyltransferase in several cancers." (PMID 31771617, 2019). "The roles of IL‐6 in the pathogenesis of cancer are well reported." (PMID 31246342, 2019).
cancer (continued). "Thus, as a key in physiological process, NF-κB not only activates inflammatory proteins like IL-6 but activates long non-coding RNA and other process in repair and cancer." (PMID 31527064, 2019). "IL-6 activation also promotes tumorigenesis by altering gene expression for the induction of cell proliferation, progression of the epithelial to mesenchymal transition, and resistance to anti-cancer drugs such as erlotinib." (PMID 30894857, 2019). "Thus, there are many PKR-triggered pathways that can lead to IL-6 production and inhibition of cancer cell proliferation." (PMID 31921696, 2019). "For this, we analyzed IL6 expression and cancer cell stemness under FA2H down- and up-regulation." (PMID 31709178, 2019). "IL‐6 is a pluripotent cytokine that is principally secreted by macrophages during the acute phase response, inflammation, bone catabolism, hematopoiesis, and cancer progression." (PMID 31094067, 2019). "Therefore, inhibition of NF-κB and IL-6 induce apoptosis progression in cancer cells and investigated as an imperative target to control cancer progression." (PMID 31450709, 2019). "In addition to its deleterious effects on inflammation and cancer, IL‐6 has been shown to have a regenerative and antiinflammatory potential (Naseem, Hussain, & Manzoor, 2018)." (PMID 31094067, 2019). "Indeed, the enhancing effects of aADSCs on the proliferation of cancer cells were blocked by the IL-6 antibody." (PMID 31196220, 2019). "In patients with cancer cachexia, cytokines, such as interleukin (IL)-1, IL-6, and tumor necrosis factor (TNF)-α, are transported across the blood-brain barrier, and induce anorexia by modulating the hypothalamic areas of the brain, the key region for appetite regulation." (PMID 30754663, 2019). "In addition, IL-6 levels were reported to be significantly higher among advanced HCC cases (Cancer of the Liver Italian Program score >3) (p = 0.003)." (PMID 29963457, 2018). "Moreover, inflammatory cells and cytokines demonstrably support cancer stem cells via the IL-6/STAT3 pathway." (PMID 30104473, 2018). "However, IL-6 has been shown to induce anti-apoptotic pathways in certain cancers, thus attenuating the efficacy of this drug." (PMID 30671025, 2018). "We therefore defined the species-conserved healing wound cytokines (HWCs) as SPP1, IL1B and IL6, and considered whether the expression levels of these genes might have prognostic value in human cancers." (PMID 30054470, 2018). "In addition, BMDMs incubation with SC144-treated cancer-derived exosomes resulted in a reversal of the IL-6 secretion phenotype." (PMID 29867925, 2018). "In addition, NF-κB is recruited to the IL-6 promoter to increase IL-6 transcriptional activity in cancer cells." (PMID 30266897, 2018). "Furthermore, many studies have shown the importance of STAT3 in the muscle wasting process in a variety of IL-6-dependent models of cancer cachexia." (PMID 29849089, 2018). "Interleukin (IL)-8 and IL-6 both play an important role in various cancer signaling pathways." (PMID 29899223, 2018). "We also observed morphological changes in the cancer cells following IL-6 treatment." (PMID 30308035, 2018). "We assessed the diagnostic value of IL-6 in the hope of finding methods to detect the GI cancers earlier, but IL-6 has little value as independent single diagnostic biomarker, since it is not cancer specific and not sensitive enough." (PMID 30038723, 2018). "Also, IL-6 can play a central role in cancer invasion and spreading, and it has been reported that in the presence of increasing levels of IL-6, both the OS and PFS of CRC patients worsened." (PMID 29351242, 2018). "Cancer cells, regarded as exogenous factors, could induce the production of inflammatory cytokines, such as interleukin‐6 (IL‐6), tumor necrosis factor (TNF) and vascular endothelial growth factor (VEGF)." (PMID 30259688, 2018). "Previous studies also suggested that serum IL-6 was a useful predictor for cancer immunotherapy." (PMID 29293510, 2018).
cancer (continued). "Higher colony numbers of C4‐2sc and CWRsc cells than those of C4‐2siIL‐6/CWRsiIL‐6 cells were detected after coculture with NK92 cells, suggesting higher resistance of IL‐6‐expressing cancer cells to the cytotoxic action of NK cells than that of IL‐6‐knockdown cells (data with primary NK cells)." (PMID 28865178, 2018). "Celastrol, a substance derived from Trypterygium wilfordii, used in traditional Chinese medicine and known for anti-cancer and anti-inflammatory effects, was used for IL-6 and IL-8 inhibition, while Maraviroc, a competitive CCR5 antagonist and anti-HIV drug, served as a RANTES/CCL5 inhibitor." (PMID 30524392, 2018). "IL6 has been shown to be involved in cancer stem cell induction and maintenance." (PMID 30218041, 2018). "The human IL-6 gene is located on chromosome 7p21 which is identified as pro-inflammatory cytokine, and plays an important role in the pathogenesis of several types of cancers." (PMID 29552316, 2018). "Similarly, research in obese non-cancer patients report reductions in serum cytokine levels and lipid profiles including IL-6, TNF-α, and cholesterol." (PMID 30450163, 2018). "In those cancer types where IL-6 has been shown to play a pro-tumoural effect, it may well be that the ER pathway is less important than it is in BC." (PMID 29256156, 2018). "Here, we provide direct evidence to support that USP24 promotes IL-6 expression, which might be beneficial for cancer therapy." (PMID 30266897, 2018). "IL-6 siRNA, Dia, and 5-Aza inhibited cancer cells invasion in Hypoxic environment individually." (PMID 29695771, 2018). "Indeed, we have recently shown that cancer cells activate breast stromal fibroblasts in an IL-6-dependent manner." (PMID 30410668, 2018). "However, the persistent IL-6 synthesis leads to the development of various diseases, including cancers." (PMID 30175384, 2018). "IL-6 and IL-8 also enable the microenvironment to promote cancer progression by promoting migration and matrix metalloprotease (MMP) production in dermal fibroblasts, bone resorption and osteolytic metastases though cyclooxygenase-2 (Cox-2)/prostaglandin E2 (PGE2)." (PMID 30119678, 2018). "Transcripts of Versican, Vegf-c, Bcl-2, Mmp-9, Il-6 and KC were up-modulated in pituitaries isolated from transgenic mice; in in vitro studies, exogenous hCG has been shown to up-modulate transcription and expression of these molecules in cancer cells." (PMID 30410667, 2018). "In PCa patients, IL-6 serum levels correlate with cancer progression and metastatic disease." (PMID 29441069, 2018). "The mechanisms that control macrophage activation in cancer, particularly induced by IL-6, remain largely unknown." (PMID 29422647, 2018). "In the studies assessed in this review, sensitivity and specificity were not convincingly high, nor superior to other diagnostic methods such as serum CEA and CA 19-9, and many cancers would not be detected with IL-6 as the diagnostic biomarker." (PMID 30038723, 2018). "IL-6 is a valuable target for treatment of dysimmune diseases and cancers." (PMID 29651420, 2018). "Thus, anti-IL-6 antibodies have been used in the treatment of patients with various cancers and inflammatory diseases." (PMID 30064449, 2018). "Furthermore, parthenolide inhibited the IL-6-induced cancer cell migration and preferentially inhibited the growth of cancer cells that had constitutively activated STAT3." (PMID 29921758, 2018). "Furthermore, the interplay between cancer cells and fibroblasts in terms of interleukin 6 expression was observed." (PMID 29435153, 2018). "Additionally, IL-6 is a main contributor of the severe immune and metabolic alterations that characterize advanced cancer and contribute to the pathogenesis of CRA." (PMID 30294279, 2018). "However, this study prompts the wider need to consider the importance of IL-6 in the macrophage response in both wound healing and cancer." (PMID 30054470, 2018).
cancer (continued). "Almost all inflammatory and infectious processes and types of cancer are associated with a strong induction of circulating IL6 levels but also in a lesser extent various non-pathological conditions such as exercise and pregnancy." (PMID 30158466, 2018). "Interestingly, especially at a later stage of hepatocarcinogenesis, HcPCs acquire an autocrine IL-6 loop due to an intracellular degradation of miRNA Let-7, leading to aggravated cancer progression." (PMID 29899223, 2018). "The study of Kothari and associates demonstrated that IL-6 induces macrophage expression of MMP-9 via Cox-2-dependent and Cox-2-independent mechanisms, which has been directly associated with the pathogenesis of chronic inflammatory diseases and cancer." (PMID 30154846, 2018). "Interleukin-6 is a key cytokine, which involves in various pathological and physiological processes of inflammatory reaction and proliferation and differentiation of various malignant tumor cells." (PMID 30369945, 2018). "Cancer stromal fibroblasts play an important role in IL-6 production and cancer progression." (PMID 30308035, 2018). "Several cytokines, especially IL-6 and IL-8, may have a significant influence on cancer progression." (PMID 29348540, 2018). "Similarly, IL-6-activation of the NF-κB pathway has also been shown to contribute to cancer cell growth." (PMID 29707119, 2018). "For instance, cachectic cytokines such as tumour necrosis factor-α (TNF-α), interferon-γ (IFN-γ), and different interleukins (ILs., e.g. IL-1β and IL-6) may be increased in the peripheral circulation of cancer patients and induce cancer cachexia." (PMID 29609556, 2018). "The CXCR4-SDF1 axis is known to promote IL-6 expression in numerous cancers, including MM, and other studies have also indicated that IL-6 may promote CXCR7-SDF1 or CXCR4-SDF1 signaling, and as such promote bone-homing." (PMID 30671025, 2018). "Targeting IL-6 may improve OS in patients with GI cancer and decrease severe cancer symptoms like fatigue and cachexia and improving quality of life in these patients." (PMID 30038723, 2018). "To examine the effects of IL-6 on cancer progression, we conducted a migration assay." (PMID 30308035, 2018). "More recently, Meads and collaborator demonstrated that PYK2 is positioned upstream of JAK1/STAT3 signaling and that it is a critical mediator of a novel survival pathway activated in the context of co-stimulation of cancer cell and the microenvironment through especially IL-6." (PMID 29455640, 2018). "Moreover, IL-6 secreted by CAFs increases cancer cell survival and resistance to tamoxifen treatment in luminal breast cancer." (PMID 29883428, 2018). "Leukemic patients present significantly higher proinflammatory cytokines, such as tumor necrosis factor alpha (TNF-alpha) and interleukin 6 (IL-6), at the onset of disease and before cancer therapies, confirming the presence of an inflammatory status in these patients." (PMID 29983896, 2018). "Interestingly, a recent study found that stromal IL-6 was actually released by adipocytes adjacent to cancer cells." (PMID 30013512, 2018). "In addition, IL-6 signaling, a type of inflammatory cytokine signaling that can influence cancer development and progression, was also reduced (z-score, -1.5)." (PMID 30308035, 2018). "MDSCs produce IL-6, which promotes the phosphorylation of STAT3, and the production of nitric oxide, in turn activating Notch signal, which causes prolonged STAT3 activation and supports cancer cell stemness." (PMID 30154786, 2018). "Several early phase clinical studies with IL-6 targeting agents currently support the hypothesis that IL-6 may be indeed an effective anti-cancer target." (PMID 29946544, 2018). "Recent studies indicated the existence of a correlation between IL-6 expression and cancer cell." (PMID 29693005, 2018). "We also suggest that IL-6 might induce WAT atrophy during cancer cachexia by accelerating WAT lipolysis and browning." (PMID 29338749, 2018).
cancer (continued). "Our findings indirectly indicate, however, that adipocyte-derived IL-6 and leptin might influence collagen reorganization, further promoting cancer metastasis, though confirmation of this hypothesis will require further experimentation." (PMID 30563531, 2018). "Importantly, the anti-IL-6 antibody mitigated the impact that cancer cells have on the gut microbiota composition, as shown in the Principal Coordinate Analysis plot of the Morisita-Horn beta-diversity index." (PMID 29719601, 2018). "Given that ERs usually act as transfection factors in cancer cells, the existence of potential EREs indicated that ERβ might contribute to IL6 expression in this way, which requires further investigation." (PMID 29970138, 2018). "IL-6, similar to many core inflammatory factors, is increased by a large amount in the inflammatory microenvironment of cancer cells; this occurs through the induction of CRP, which activates the NF-κB pathway to reduce the activity of caspase-3 and inhibit the apoptosis of cancer cells." (PMID 30647533, 2018). "Fifth, IL-6 inhibition therapy may be an effective treatment for certain cancers in which IL-6 promotes proliferation." (PMID 30423923, 2018). "Indeed, let-7b inhibitor Lin28B, is up-regulated in response to the induction of the IL-6 feedback loop in both cancer and fibroblast cells." (PMID 29707149, 2018). "IL-6 promotes cancer cell proliferation and cancer cell metastasis via the PI3K and MAPK pathways." (PMID 29794990, 2018). "The link between PLCγ1 activity and the IL-6/STAT3 signaling pathway could account for the transcription of many important cancer-related genes." (PMID 29464031, 2018). "Also, since inflammation is an identifiable factor associated with malignancy, we were interested in determining if higher serum IL6 and IL8 levels were associated with cancer development in people with A-T over time." (PMID 30586396, 2018). "Activation of IL-6/IL-6R and its downstream was found in hypoxic cancer cells." (PMID 29695771, 2018). "Levels of IL-6 play a role in proliferation of cancer cells in solid tumors." (PMID 29963457, 2018). "IL6 is necessary for some cancer cells to grow and thus inhibition of this pathway could be therapeutic." (PMID 30515152, 2018). "In line, TNFα and IL-6 levels are elevated in the serum of cancer patients." (PMID 30591653, 2018). "Thus, both RANTES/CCL5 and IL-6 are molecules that were upregulated upon dsRNA transfection of cancer cells at the protein level as determined by two complementary methods." (PMID 30613350, 2018). "Gemcitabine targets fast-replicating cancer cells and resistance to this drug may also be tied to IL-6, as evidenced by a study where gemcitabine-resistance was observed in cancer cells treated with IL-6 and sIL-6R." (PMID 30671025, 2018). "IL-6 signaling has been shown to promote tumorigenesis by regulating cancer metabolism, increasing cancer cell growth and self-renewal, as well as resistance to apoptosis, boosting invasiveness and metastasis, regulating angiogenesis, and sustaining RANKL expression and bone resorption." (PMID 30154786, 2018). "Studies of HNSCC have shown that these cancers express high levels of Interleukin-6 (IL-6), and both autocrine and paracrine signaling have been hypothesized as mechanisms for their IL-6 mediated growth dynamics." (PMID 29351275, 2018). "Previous studies have discussed the correlation between MSCs and IL6 in the progression of cancer." (PMID 30346985, 2018). "Under in vitro conditions, they stimulated cancer cell proliferation (via IL-6), migration (via CXCL8/IL-8 and CCL2/MCP-1), and invasion (via IL-6, MMP-3 and uPA), and they triggered the EMT in a mechanism involving TGF-β1-dependent induction of Smad 2/3-Snail1 signaling." (PMID 28956065, 2018). "In addition, IL-8 treatment increased cancer malignancy, indicating that not only IL-6 but also other factors regulated by USP24 modulate cancer malignancy." (PMID 30266897, 2018).